STAT3 (signal transducer and activator of transcription 3)
Diseases named in the same sentence as STAT3 in open-access papers (continued):
Sharing a sentence is not in itself a finding about the gene and the disease.
breast cancer (continued). "SDC1 relies on the IL-6/STAT3, Notch and EGFR pathways to induce stem cell formation in breast cancer, Ibrahim et.al." (PMID 41364407, 2025). "Therefore, targeting the STAT3 pathway may be a therapeutic method for breast cancer." (PMID 40830747, 2025). "In this study, we identified circRNA-14,052 as a novel oncogenic circRNA that promotes breast cancer progression by sponging miR-214-3p and upregulating IKBKB, thereby activating the IL-6/JAK2/STAT3 signaling axis." (PMID 41044672, 2025). "For instance, in breast cancer cells, MARCH8 ubiquitinates STAT3 and CD44, suppressing tumor metastasis, while in hepatocellular carcinoma, MARCH8 induces degradation of PTEN thereby promoting malignancy." (PMID 41023307, 2025). "More specifically, constitutive STAT3 activation alone is found in about 40% of cases, and constitutive activation of both STAT3 and STAT5 is found in about 30% of breast cancer cases." (PMID 40507264, 2025). "Mechanistically, M2 enhances tumor survival via pathways like CCL2/PI3K/Akt/mTOR in breast cancer, IL-6/STAT3 in colon and pancreatic cancers, and CHI3L1 in gastric/breast cancers." (PMID 40940877, 2025). "We investigated the expression pattern of the JAK-STAT signaling pathway in these four breast cancer cell lines and observed high activation of JAK2 and STAT3 in TNBC cell lines." (PMID 40199813, 2025). "The STAT3 protein was identified as a therapeutic target in TNBC due to its substantial involvement in tumor growth, metastasis, and developing breast cancer stem cell-like properties." (PMID 41325388, 2025). "In breast cancer, leptin secreted by adipocytes regulates therapeutic resistance and self-renewal ability of CSCs by activation of JAK/STAT3 signaling pathway, which leads to increased levels of the FAO enzyme carnitine palmitoyl transferase 1B." (PMID 40647402, 2025). "After administration, BO significantly downregulated STAT3 in the MDA-MB-231 and MCF-7 breast cancer cell lines." (PMID 40076902, 2025). "KLF14 inhibited the migration of breast cancer cells and the polarization of M2 macrophages via altering the signaling pathways of SOCS3/RhoA/Rock/STAT3." (PMID 39858015, 2025). "Some studies suggest that STAT3 can promote metastatic potential and cancer stem cell properties in HER2-overexpressing breast cancer cells." (PMID 40507264, 2025). "In breast cancer, CD155 can enhance mitochondrial fatty acid β-oxidation via the CD155-CD96-Src-Stat3-Opa1 signaling axis, thereby promoting the chemotherapy resistance of breast cancer stem cells." (PMID 40217455, 2025). "Through the TIMER2.0 database, we found that STAT3 was positively correlated with programmed death‐ligand 1 (PD‐L1, CD274) expression in breast cancer, and this correlation was more pronounced in BRCA‐Basal‐type breast cancer." (PMID 40918170, 2025). "Heterogeneity observed in breast cancer lines (e.g., MCF-7+ vs. MDA-MB-231−) suggests context-dependent regulation, potentially involving STAT3 or Wnt/β-catenin signaling." (PMID 40873574, 2025). "Research by Yujie Li has shown that DLGAP5 regulates breast cancer cell proliferation, migration, invasion, and the cell cycle via the JAK2/STAT3 signaling axis." (PMID 40406126, 2025). "Other compounds, including C‐pTyr–Leu–Pro–Gln–Thr–Val–NH2, BP–PM6, BP–PM7, and PMM‐172, have been shown to suppress STAT3 by reducing its persistent phosphorylation in HNSCC and breast cancer through SH2 domain inhibition." (PMID 40166646, 2025). "Wang et al8 have reported in breast cancer that the JAK/STAT3 signaling can facilitate the transcription of CPT1B, thereby promoting FAO and sustaining the proliferation of breast cancer stem cells as well as their chemoresistance." (PMID 41340257, 2025). "This review will focus on STAT3 and STAT5 in normal breast physiology and breast cancer, and the competing roles they play in normal and malignant development, specifically focusing on their role as transcription factors." (PMID 40507264, 2025).
breast cancer (continued). "In breast cancer cells resistant to palbociclib, re-sensitization to the drug is achieved by combining inhibitors against PARP and STAT3." (PMID 40843360, 2025). "In breast cancer, lactate enhances the M2 phenotype by activating the extracellular signal-regulated kinase (ERK)/signal transducer and activator of transcription 3 (STAT3) signaling pathway, which increases the invasion and growth of breast cancer cells." (PMID 40421024, 2025). "Elucidate the critical roles of exosomes in modulating breast cancer behaviour and disease progression in TNBC through STAT3 signaling pathways." (PMID 40952540, 2025). "In breast cancer, macrophage-derived CXCL1 activates an IGF1R/STAT3/HMGB1 axis that promotes autophagy-mediated paclitaxel resistance and inhibits apoptosis." (PMID 41465435, 2025). "This study establishes STAT3 as a key prognostic biomarker in breast cancer and demonstrates the clinical potential of our validated DCE-MRI radiomics model for noninvasive STAT3 assessment." (PMID 40636126, 2025). "Developing a better understanding about the roles that STAT3 and STAT5 play in breast cancer will be important for successful treatment in the future." (PMID 40507264, 2025). "The third is the CD155/CD96/Src/STAT3/Opa1 pathway, which enhances FAO in breast cancer stem cells (BCSCs)." (PMID 40002245, 2025). "Specifically, STAT3 and STAT5 have been extensively researched in the context of breast cancer due to their important roles in normal mammary gland development and function." (PMID 40507264, 2025). "In locally advanced HER2-positive breast cancer, IL-8 undermines the efficacy of lapatinib by activating the SRC/STAT3/ERK1/2 signaling cascade, which in turn stimulates the EGFR pathway." (PMID 40092996, 2025). "EGFR is a receptor tyrosine kinase that promotes the proliferation and invasion of breast cancer by stimulating multiple oncogenic pathways such as Ras-Raf-MEK-ERK, PI3K-AKT-mTOR, and Src-STAT3." (PMID 40454580, 2025). "Breast cancer treatment involves targeting key genes involved in cell proliferation, differentiation, and apoptosis, such as PIK3CA, CCND1, HER2, STAT3, WNT1, and KRAS." (PMID 40284420, 2025). "In silico data showed that breast cancer patients of TCGA exhibited a positive correlation between the gene expression of the APE1 redox function signature and the STAT3 signature, which corroboratesour in vitro findings." (PMID 41090323, 2025). "Visfatin has been demonstrated to induce proliferation of breast cancer cells proliferation via the extracellular signal-activated kinase (ERK1/2), protein kinase B (AKT), and signal transducer and activator of transcription 3 (STAT3) pathways." (PMID 39561117, 2025). "Nevertheless, the stemness maintenance and survival of CSC has been demonstrated to be based on the activation of STAT3 and, particularly, IL6/JAK/STAT3 is activated in breast cancer stem cells." (PMID 39859345, 2025). "In normal mammary gland development and breast cancer, JAK2 is the primary activator of both STAT3 and STAT5." (PMID 40507264, 2025). "TGF-β1/SMAD/HLF-activated IL-6 in TNBC cells induces a TAM-like phenotype via the JAK/STAT3 pathway and further upregulates TGF-β 1 expression, constituting a feedback circuit that promotes breast cancer ferroptosis resistance." (PMID 39858015, 2025). "A recent study found that STAT3 interacts with the promoter sequence of SREBP2 and increases the expression of SREBP2 in breast cancer cells." (PMID 40713894, 2025). "Another study showed that the STAT3 pathway is positively regulated by mTOR signaling, while PTEN functions as a negative regulator of both STAT3 and mTOR pathways in breast cancer." (PMID 41287778, 2025). "Silibinin downregulates the expression of the key migration regulators MMP-2 and MMP-9 through the Jak2/STAT3 and MEK/ERK pathways in breast cancer." (PMID 41470858, 2025).
breast cancer (continued). "The first pathway involves the phosphorylation of STAT3, which binds to the CD36 promoter, inducing its transcription and promoting fatty acid uptake in breast cancer cells." (PMID 40002245, 2025). "NDRG2 overexpression in breast cancer (BC) significantly inhibited tumor cell growth by attenuating Janus tyrosine kinases (JAK2) and STAT3 pathways." (PMID 40378957, 2025). "Breast cancer cells enhance tumor survival by HER2 signaling, while astrocyte-derived STAT3 and cytokines such as interleukin-6 (IL-6) and interferon-alpha (IFNα) protect tumor cells from apoptosis." (PMID 41429896, 2025). "In HER2-overexpressing SKBR3 breast cancer cells with trastuzumab resistance, STAT3/HIF-1α axis-mediated Hes1 induction downregulates PTEN, positioning Hes1 as a pivotal node linking STAT3 signaling to PTEN suppression." (PMID 40755759, 2025). "In breast cancer, progranulin increases PD‐L1 expression in TAMs via the JAK/STAT3 signaling pathway and promotes the M2 polarization of TAMs." (PMID 40051246, 2025). "In this study, Yang and colleagues also demonstrated that silencing CXCL1 or blocking IGF1R/STAT3 signaling disrupts this HMGB1–autophagy–MRPs axis and restores drug sensitivity in breast cancer." (PMID 41465435, 2025). "In breast cancer, STAT3 promotes ferroptosis by increasing ACSL4 expression, while in ulcerative colitis (UC) cell models, STAT3 phosphorylation is downregulated, and the ferroptosis inhibitor Fer-1 can restore its phosphorylation." (PMID 40165005, 2025). "At the same time, the expression of STAT3 and vasodilators stimulating phosphorylated protein (VASP) mRNA was found to be upregulated in MCF-7 breast cancer cells." (PMID 41011202, 2025). "While the literature on the interplay between STAT3 and NRF2 is limited, our results are consistent with a previous report showing a significant correlation between STAT3 and NRF2 in breast carcinoma tissues." (PMID 40317079, 2025). "In conclusion, C6 ceramide inhibits canine mammary cancer growth and metastasis by targeting EGR3 through the regulation of the JAK1/STAT3 signaling pathway." (PMID 38338065, 2024). "Altogether, these results suggest that AM-18002 is an effective STAT3 inhibitor and MDSC depletion inhibited the migration and invasion of breast cancer cells." (PMID 38625901, 2024). "IDO1 is highly expressed and promotes metastasis, drug resistance, cell proliferation, and TAM resistance through STAT3 and interleukin-6 in TAM-resistant breast cancer." (PMID 38539263, 2024). "In breast cancer, the PPARγ ligand pioglitazone has been shown to act as a tumor suppressor via the JAK2/STAT3 signaling axis." (PMID 39770941, 2024). "The inhibition of STAT3 phosphorylation has reduced the expression of matrix metallopeptidases MMP2 and MMP9, which help enable breast cancer invasion and metastasis." (PMID 38935814, 2024). "DHA suppressed breast cancer cell growth and promoted apoptosis in DDP (cisplatin)-resistant cells by inhibiting STAT3/DDA1 signaling." (PMID 38397437, 2024). "A mouse model study has shown that EGFR/Stat3 and TGF-β/Smad signaling is required for autophagy functions in two distinct breast cancer stem-like cells CSCs (ALDH+ and CD29high/CD61+, respectively)." (PMID 39201332, 2024). "STAT3 is a central mediator of EMT transcription factors and is often overexpressed and/or hyper-activated in many cancers including breast cancers." (PMID 39199680, 2024). "In breast cancer and bladder cancer, CD44 knockdown inhibits cell invasion and tumorigenicity by blocking STAT3 phosphorylation." (PMID 38385088, 2024). "Using multiple breast cancer cell line models (MDA-MB-468, BT-549, HCC-1954), we identified STAT-3 signaling to be a cell line-dependent factor determining cancer cell survival following LDHC silencing." (PMID 39001513, 2024). "Collectively, our results demonstrate that SUSD2 expression is mediated by STAT3 and imply the potential of using SUSD2 as a biomarker to stratify HER2+ breast cancer." (PMID 39791720, 2024).
breast cancer (continued). "In these cancer cells, the active phosphorylated form of STAT3 interacts directly with the Neh1 and Neh3 domains of NFR2, and the concurrent binding of STAT3 and NRF2 to IL23A promoter accelerates breast cancer cells growth." (PMID 38755517, 2024). "In conclusion, our research elucidates the critical function of CCT2 in breast cancer progression, primarily via the initiation of the JAK2/STAT3 signaling cascade." (PMID 39079960, 2024). "It has been found that miRNA‐101 regulates the apoptosis of breast cancer cells and brain cell apoptosis through the JAK2‐STAT3 pathway by reducing JAK2 protein expression and inhibiting STAT3 protein." (PMID 38517042, 2024). "In activated B-cell-like diffuse large B-cell lymphoma and breast cancer cells, two E3 ligases, Fbw7 and MARCH8, were reported to degrade STAT3, respectively 43,44." (PMID 39479456, 2024). "MiR-20 is a T-helper cells modulator which affects breast cancer by targeting FOXO-1 and STAT3 pathway." (PMID 38726321, 2024). "In breast cancer, the SOST gene was found to interact with signal transducer and activator of transcription 3 (STAT3) and enhance TGF-β/KRAS (Kirsten rat sarcoma virus) signaling, leading to increased tumor growth and bone metastasis." (PMID 38247829, 2024). "piR-2158 affects breast cancer biology via the targeting of IL11, leading to lower phosphorylation of STAT3 and impairment of JAK/STAT3 pathway, responsible for the dysregulation of angiogenesis and self-renewal of breast CSC." (PMID 38303021, 2024). "Treatment of BT549 cells (TNBC), SK-BR-3 cells (HER2+ breast cancer), and SK-OV-3 cells (late stage, invasive ovarian cancer) with 200 μg/mL of BP1003 for 96 h resulted in a 30–40% decrease in STAT3 protein levels compared to cells treated with EL." (PMID 39200368, 2024). "Functional analysis revealed that CCT2 promoted breast cancer growth and metastasis through activation of the JAK2/STAT3 signaling pathway." (PMID 39079960, 2024). "LIFR is known to activate STAT3, ERK, and AKT signaling, among numerous other signaling pathways in breast cancer." (PMID 38409028, 2024). "In breast cancer cases, HDACis can inhibit metastasis and growth through the IL - 6/STAT3 signaling pathway, while AR antagonists can enhance the antitumor effects of PARP inhibitors in AR-positive breast cancer by regulating the DNA damage response." (PMID 38594722, 2024). "MDA-MB-231 breast cancer cells are highly metastatic due to the presence of metastatic proteins like MRTF-a and STAT3." (PMID 39065626, 2024). "MUC16 has been reported to take part in breast cancer progression and metastasis when overexpressed due to its influence on cell cycle and survival through the JAK2/STAT3 pathway." (PMID 39723380, 2024). "This indicates that breast cancer cells can downregulate DCN and activate NBFs in an IL-6-dependent manner, through the activation of STAT3/NF-κB signaling." (PMID 38667295, 2024). "In this context, STAT3 collaborates with SHOX2 to form a functional immunocomplex, thereby enhancing the transcriptional activity of WASF3 in breast cancer cells and promoting breast cancer metastasis." (PMID 38429660, 2024). "Numerous studies have shown that the UPR can promote the proliferation of tumors such as liver cancer, melanoma, and breast cancer through various signaling cascades such as IRE1/XBP1/JNK, IRE1/XBP1/IL-6/STAT3, and IRE1/TRAF2/NF-κB." (PMID 39080273, 2024). "Our study first demonstrated the anti-tumor effects of TEC against breast cancer and lung cancer via inhibition of the JAK2/STAT3 signaling and further revealed the potential role of metochalcone in restricting tumor growth in vivo." (PMID 38686052, 2024). "By activating the VEGFR2/STAT3 pathway, VEGF induces the upregulation of Myc and Sox2 expression, thereby promoting the self-renewal of breast cancer stem cells." (PMID 38699644, 2024).
breast cancer (continued). "Abeceline mesylate, as a therapeutic drug for breast cancer, can also inhibit the level of proinflammatory cytokines mediated by LPS by downregulating AKT/STAT3 signal transduction, and improve the status of AD diseases." (PMID 39346794, 2024). "We previously demonstrated that tGLI1 and STAT3 oncogenic transcription factors directly interact and functionally promote the aggressiveness of HER2-enriched breast cancer and TNBC." (PMID 39768178, 2024). "We also show that whereas the upregulation of MRP1 and MDR1 is a direct target of NF-κB activity as reported by others in breast cancer, the upregulation of BCL-xL is an indirect target via the autocrine IL-6/STAT3 loop as reported in liver cirrhosis." (PMID 38806726, 2024). "Our results show that upon the knockdown of MALAT-1, a marked repression of STAT-3 and CSE was observed, thereby highlighting MALAT-1 as a novel upstream lncRNA regulating the STAT-3/CSE/ H2S axis in breast cancer." (PMID 38250807, 2024). "In the present study, we identified a novel combinatorial therapy through pharmacological inhibition of tGLI1 and GP130, an upstream regulator of STAT3, in HER2-enriched breast cancer and TNBC." (PMID 39768178, 2024). "In particular, the constitutive active form of STAT3 has been detected in more than 50% of breast cancers, suggesting that the JAK2-STAT3 pathway plays an important role in breast cancer tumorigenesis." (PMID 38872110, 2024). "In this article, the expression of CHI3L2 in the cytoplasm of IDC and breast cancer cell lines is presented for the first time, and the influence of CHI3L2 protein on the phosphorylation of STAT-3 and ERK1/2 signaling pathways is discussed." (PMID 39557919, 2024). "It is worth noting that several studies have indicated that STAT3, a member of the STAT family, is an oncogene and is aberrantly activated in various malignant tumors, including breast cancer." (PMID 39845783, 2024). "TGLI1 and STAT3 transcription factors interact to co-regulate target genes, Cep70, UPF3A, and RRas2, to mediate aggressive phenotypes in breast cancer." (PMID 39768178, 2024). "Here, we analyzed protein expression of tGLI1, GP130, phosphorylated STAT3 (pSTAT3-Y705), and total STAT3 in normal mammary cell lines in addition to luminal A, luminal B, HER2-enriched, and TNBC breast cancer cell lines." (PMID 39768178, 2024). "CXCL1 knockdown in TAMs demonstrated a remarkable chemosensitizing effect on breast cancer xenografts, along with blockage of IGF1R/STAT3/HMGB1 signaling in vivo." (PMID 39394189, 2024). "In breast cancer and prostate cancer, RKIP blocks signal transducer and activator of transcription 3 activation." (PMID 38914697, 2024). "CDDO-Im has been shown to be a potent inhibitor of the epidermal growth factor receptor (EGFR) and STAT3/SRY-Box transcription factor 2 (Sox-2) signaling pathways in tumor-inducing macrophage (TIM) cells, which stimulate breast cancer growth and metastasis." (PMID 39064870, 2024). "In a variety of tumor cells, including gastric cancer, glioblastoma, and breast cancer, the activation of the CXCL12/CXCR4 axis has been observed to stimulate the SRC, ERK, and STAT3 pathways." (PMID 38920657, 2024). "In breast cancer, tumor-derived lactate was reported to induce macrophage towards M2-polarization via ERK/STAT3 pathway." (PMID 38576043, 2024). "Emerging studies have discovered that STAT3, p300 and MMP19 are overexpressed in breast cancer, esophageal cancer, colorectal cancer (CRC) or NSCLC and so on, promoting cancer cell growth or metastasis." (PMID 38560562, 2024). "Collectively, our research highlights the important role of TAMs/CXCL1 in mediating breast cancer chemoresistance through the regulation of autophagy, and proposes IGF1/IGF1R as a potential upstream signaling that governs autophagy via STAT3/HMGB1 activation." (PMID 39394189, 2024).